HTR4 (5-hydroxytryptamine receptor 4)
Description:
G protein-coupled receptor for 5-hydroxytryptamine (serotonin), a biogenic hormone that functions as a neurotransmitter, a hormone and a mitogen. Ligand binding causes a conformation change that triggers signaling via guanine nucleotide-binding proteins (G proteins) and modulates the activity of downstream effectors. HTR4 is coupled to G(s) G alpha proteins and mediates activation of adenylate cyclase activity.
Synonyms: 5-HT4; 5-HT4R
Tractability: Small molecule: an approved drug acts on it; a structure with a bound ligand is known; a high-quality ligand is known; it belongs to a druggable protein family. Antibody: UniProt places it where antibodies can reach, with high confidence; its Gene Ontology location is reachable by antibodies, with high confidence; UniProt predicts a signal peptide or a membrane-spanning region. PROTAC: a small molecule that binds it is known.
Target class: Monoamine receptor; Family A G protein-coupled receptor; Small molecule receptor (family A GPCR); Serotonin receptor; Membrane receptor
Chemical probes: CHEMBL1258452, CHEMBL1632158
Safety:
Unwanted effects reported when the protein is acted on. In parentheses: how it was acted on, where the effect was seen, and who reports it.
decreased anxiety (inhibition, acute dosing; central nervous system, cardiovascular, gastrointestinal; source: Lynch et al. (2017))
decreased blood pressure (activation, acute dosing; central nervous system, cardiovascular, gastrointestinal; source: Lynch et al. (2017))
decreased blood volume (activation, acute dosing; central nervous system, cardiovascular, gastrointestinal; source: Lynch et al. (2017))
decreased gastrointestinal transit (inhibition, acute dosing; central nervous system, cardiovascular, gastrointestinal; source: Lynch et al. (2017))
diarrhea (activation, acute dosing; central nervous system, cardiovascular, gastrointestinal; source: Lynch et al. (2017))
fainting (activation, acute dosing; central nervous system, cardiovascular, gastrointestinal; source: Lynch et al. (2017))
increased gastric emptying (activation, acute dosing; central nervous system, cardiovascular, gastrointestinal; source: Lynch et al. (2017))
increased gastrointestinal transit (activation, acute dosing; central nervous system, cardiovascular, gastrointestinal; source: Lynch et al. (2017))
increased heart rate (activation, acute dosing; central nervous system, cardiovascular, gastrointestinal; source: Lynch et al. (2017))
increased memory (activation, acute dosing; central nervous system, cardiovascular, gastrointestinal; source: Lynch et al. (2017))
increased QTc interval (activation, acute dosing; central nervous system, cardiovascular, gastrointestinal; source: Lynch et al. (2017))
Gene: Protein-coding gene on chromosome 5 (148,446,042 to 148,677,235, reverse strand). Ensembl gene ENSG00000164270.
Subcellular location: Cell membrane; Endosome membrane
Pathways (Reactome):
Signal Transduction: G alpha (s) signalling events; Serotonin receptors
Gene Ontology:
Molecular function: G protein-coupled serotonin receptor activity; protein binding; serotonin receptor activity; neurotransmitter receptor activity; serotonin binding; G protein-coupled receptor activity
Biological process: adenylate cyclase-activating G protein-coupled receptor signaling pathway; adenylate cyclase-activating serotonin receptor signaling pathway; large intestinal transit; adenylate cyclase-inhibiting serotonin receptor signaling pathway; chemical synaptic transmission; G protein-coupled receptor signaling pathway; G protein-coupled receptor signaling pathway, coupled to cyclic nucleotide second messenger; maintenance of gastrointestinal epithelium; mucus secretion; regulation of appetite; regulation of postsynapse assembly; system process
Cellular component: cytoplasm; membrane; plasma membrane; dendrite; endosome membrane; glutamatergic synapse; postsynapse
Genetic constraint (gnomAD): Loss-of-function variants: 15 observed, 33.49 expected, observed/expected ratio (o/e) 0.45, 90% interval 0.3 to 0.69. The upper end of that interval is the gene's LOEUF score, 0.69, which puts it in group 2 of 6, group 1 being the genes least tolerant of losing a copy. Missense variants: 422 observed, 501.13 expected, observed/expected ratio (o/e) 0.84, 90% interval 0.78 to 0.91. Synonymous variants: 185 observed, 191.49 expected, observed/expected ratio (o/e) 0.97, 90% interval 0.86 to 1.09.
Homologues: Orthologues: chimpanzee HTR4 (99% identical), macaque HTR4 (98% identical), dog HTR4 (96% identical), guinea pig HTR4 (95% identical), pig HTR4 (90% identical), rabbit HTR4 (89% identical), mouse Htr4 (88% identical), rat Htr4 (88% identical), tropical clawed frog htr4 (79% identical), zebrafish htr4 (73% identical). Paralogues in human: DRD5 (32% identical), HRH2 (32% identical), DRD1 (32% identical), HTR1A (31% identical), DRD3 (28% identical), TAAR1 (28% identical), HRH1 (27% identical), HTR1D (27% identical), CHRM3 (27% identical), CHRM5 (26% identical), DRD4 (26% identical), CHRM1 (25% identical), and 13 more.